IL17A (interleukin 17A)
Diseases named in the same sentence as IL17A in open-access papers (continued):
Sharing a sentence is not in itself a finding about the gene and the disease.
influenza (continued). "Here we reveal that thymus-derived γδ T cells arise in the lung from day 1 following pdmH1N1 influenza infection and act as the predominant producers of local IL-17A." (PMID 33772013, 2021). "IL-17 KO mice expressed increased IFNs, made protective influenza-specific antibodies, and recovered from infection, suggesting that IL-17A activation exacerbates disease during infection." (PMID 34959590, 2021). "Following influenza infection, significantly reduced IL-17A production was detected in lung γδ T cells from Cd19−/− mice when compared to wild-type controls." (PMID 33772013, 2021). "Here, we reveal that endogenous lipids can be released into the extracellular milieu during influenza infection and subsequently activate γδ T cells for rapid IL-17A induction." (PMID 33772013, 2021). "This mission is followed by induction of IL-17A production, aimed at activation of protective neutrophils and NK cells in tracheal mucosa and so suppressing invasive viral replication after influenza infection." (PMID 33183352, 2020). "We observed that the early production of IL‐17A by Vγ4+ γδ T cells modulates neutrophil recruitment during influenza infection in the trachea." (PMID 31777067, 2020). "Innate B-1a cells can differentiate via IL-17A modulation into vigorous IgM-producing cells responding to influenza infections." (PMID 33266210, 2020). "In comparison, IL-17A-producing γδT cells in the lung can upregulate expression of IL-33 and amphiregulin, thereby promoting lung repair following influenza infection." (PMID 31337278, 2019). "We demonstrate that early influenza infection significantly reduced levels of pneumococcus driven IL-12p70, IL-23 and IL-27 in human monocytes with significant impairment of IL-17A and IFN-γ in HKSP-treated allogeneic mixed lymphocyte cultures." (PMID 30192848, 2018). "The importance of our research is in determining that influenza and its component haemagglutinin has a direct effect on the classic pneumococcus induced pathways to IL-17A in our human ex vivo model." (PMID 30192848, 2018). "Support for our findings is also evident in the recent reports that demonstrate that influenza HA or modified versions thereof can inhibit IL-17A and IL-6 production in mice with subsequent beneficial effects on collagen-induced arthritis." (PMID 30192848, 2018). "In contrast, memory T cells reactive toward SEB, M tuberculosis, influenza vaccine components, or tetanus toxoid showed a polarized Th1 profile with low expression of IL17A." (PMID 28782508, 2017). "In the current study, up-regulated IL-17A expression was detected in lung tissues of influenza-infected mice as early as 2 dpi." (PMID 26735852, 2016). "Based on the in vivo and in vitro analyses, we have shown that influenza infection triggers a series of rapid events in the lung where B-1a cells become IgM secreting plasma cells under the influence of IL-17A." (PMID 26735852, 2016). "Replicating our previously published data there was attenuation of production of the Type 17 effector cytokines, IL-17A, IL-17 F, IL-22, and IL-23 in the influenza, S. aureus infected WT mice compared to WT mice that received S. aureus alone." (PMID 25651926, 2015). "In this study, we report that interleukin-1β (IL-1β) and interleukin-17A (IL-17A) are key mediators of neutrophilic inflammation in influenza-induced exacerbations of chronic lung inflammation." (PMID 24918427, 2014). "We further report a role for IL-17A as a mediator of IL-1β induced neutrophilia at early time points during influenza-induced exacerbations." (PMID 24918427, 2014). "In line with this, we found that IL-17A mediated early inflammation in our model of influenza-induced exacerbations of chronic lung disease." (PMID 24918427, 2014). "pneumoniae-infected mice compared with mice given S. pneumoniae alone, suggesting that primary influenza infection appeared to lead to a selective attenuation of IL-17A." (PMID 24408967, 2014).
influenza (continued). "Taken together our data demonstrated that blocking of IL-17A or IL-1β signaling during influenza-induced exacerbations diminished neutrophilic infiltration at distinct phases of infection." (PMID 24918427, 2014). "Antibody neutralization of IL-17A during influenza infection significantly reduced the enhanced lung neutrophilic response, which was partially responsible for mediating the increased morbidity." (PMID 24465206, 2014). "While IL-6 and TGF-β1 were significantly elevated in MASLD patients with typical bacterial sCAP at admission, in MASLD patients with L. pneumophila, M. pneumoniae and influenza sCAP we observed a sharp early increase and a significant decline in IL-17A five days later." (PMID 40869413, 2025). "Furthermore, IL-17 produced by Th17 cells promotes neutrophil-driven lung and intestinal injury during influenza, yet IL-17A is also essential for mucosal repair in neonates, revealing age- and context-dependent roles." (PMID 40872830, 2025). "Using an experimental mouse model with localized nasopharyngeal influenza infection, we show that IL-17RA, a receptor for interleukin IL-17A, is a significant contributor to influenza tissue damage in the nasopharynx and promotes severe bacterial co-infection by Streptococcus pneumoniae." (PMID 38060620, 2023). "While the findings from gut inflammatory models suggest the dual role of IL-17A on epithelial barrier function, there remains a knowledge gap on IL-17-mediated regulation of epithelial inflammation and barrier integrity in the upper respiratory tract during influenza." (PMID 38060620, 2023). "Notably, IL-17 signaling was critical for acute lung injury of influenza infection and S. pneumoniae coinfection with influenza virus elicits IL-17A response causing inflammation in the nasopharynx." (PMID 37600066, 2023). "IL-33 was shown to be induced by IL-17A in γδ T cells in a mouse model of influenza infection." (PMID 35479098, 2022). "Indeed, this is illustrated in neonatal influenza infection, where a rapid γδ T cell IL-17A response is generated in the lung, which induces IL-33 in epithelial cells, leading to a pro-repair Areg response from ILC2 and Tregs." (PMID 33936115, 2021). "The IL-33/IL-17A repair axis may also operate in human infants, as nasal aspirates from children with mild influenza show positive correlations between IL-17A and IL-33 levels and also between IL-17A and Areg levels." (PMID 33936115, 2021). "Further investigations are needed to elucidate the mechanisms governing the protective, inhibitory and pathological roles mediated by IL-17A during influenza infection so that better vaccine designs can be engineered to offer potent cross-protection against evolving field strains." (PMID 33391267, 2020). "Finally, the analysis of neutrophil numbers in tracheas from infected IL‐17A/IL‐17F double KO (IL‐17AFKO) mice, confirmed the role of IL‐17 in neutrophil recruitment during influenza infection." (PMID 31777067, 2020). "Conversely, other studies found increased serum levels of IL-17A in the progression period of influenza infection, reporting that IL-17A might exacerbate lung damage and contribute to disease pathogenesis." (PMID 31061831, 2019). "For instance, interleukin-1β (IL-1β) and interleukin-17A (IL-17A) may mediate neutrophilic inflammation in influenza-initiated exacerbation of chronic lung inflammation." (PMID 31307416, 2019). "In addition, IL-17RA, which is a common receptor of IL-17A and IL-17F, is critical for neutrophil migration and lung injury after influenza infection." (PMID 31337278, 2019). "Excessive secretion of interleukin-17A (IL-17A) by Th17 cells may sustain neutrophil migration to the lungs following influenza infection, and therefore contribute to disease in severe influenza infection." (PMID 29445379, 2018).
influenza (continued). "Although IL-2, IL-4, and IL-17A may be involved in the pathogenesis of bronchial asthma and influenza infection, they were undetectable in the BAL fluid from mice in this study." (PMID 28831046, 2017). "To address whether neutrophil recruitment mediated by IL-17A was responsible for the intensified influenza-driven morbidity, we depleted neutrophils in vaccinated mice immediately prior to and during influenza challenge." (PMID 24465206, 2014). "Nevertheless, we could block the recruitment of neutrophils at early time points following the influenza infection by neutralizing IL-17A." (PMID 24918427, 2014). "Although multiple studies have addressed the basis for the inhibitory effects of IL-27 on Th1, Th2 and Th17 cell responses, this is the first study linking IL-27 to IL-17A suppression in innate γδ T cells, which sensitized the host to secondary pneumococcal pneumonia following influenza infection." (PMID 24408967, 2014). "Neutralization of IL-17A confirmed a detrimental role for this cytokine during influenza infection." (PMID 24465206, 2014). "IL-17A, a cytokine that plays a central role in amplifying inflammatory cascades by inducing a variety of chemokines and cytokines, has also been reported to contribute to the development of emphysema and to the immunopathology following influenza infections." (PMID 24918427, 2014). "To assess whether IL-17A was indeed a mediator of IL-1β driven neutrophilia we neutralized IL-17A during influenza infection of LPS/elastase treated mice." (PMID 24918427, 2014). "In conclusion, our study suggested that TLR4, CD14, MyD88, NF-κB p65, HIF1 α, VEGF, IL17A, and IL6 in the TLR4/NF-κB p65 signaling pathway and HIF-1α/IL17 signaling pathway may be the key targets for the identified active compounds of HSSD to treat influenza by inhibiting inflammatory responses." (PMID 36386710, 2022). "Thus, the TLR4, CD14, MyD88, and NF-κB p65 in TLR4/NF-κB p65 signaling pathway, HIF1 α, VEGF, IL17A, and IL6 in HIF-1α/IL17 signaling pathway may be the targets responsible for the anti-inflammatory function of HSSD in treating influenza." (PMID 36386710, 2022). "Furthermore, the partial association of HA, which is a major component of IAV vaccines, with IL-17A down-regulation may have implications for the recommended use of multiple vaccines as a whole and particularly combined influenza and pneumococcal vaccines." (PMID 30192848, 2018). "The fact that IL-27 neutralization or IL-17A administration could restore anti-pneumococcal effects opens a new door for protecting human population from secondary pneumococcal infections especially during influenza pandemics." (PMID 24408967, 2014). "We therefore measured the levels of several cytokines, including the pro-inflammatory TNF, IL-1β, IL-6, and IFN-γ, as well as IL-4, IL-10, IL-17A, and IL-22, in BAL samples from mice 5 days after influenza challenge." (PMID 40612502, 2025). "Immunokinetic patterns were pathogen-specific, including transient increase in IL-17A and IL-10 in Legionella and Mycoplasma infections, and CXCL10, IL-2, IL-17A, TGF-β1 and IL-10 in influenza." (PMID 40869413, 2025). "Huoxiang Suling Shuanghua Decoction exerts an anti-influenza effect by affecting the expressions of mRNA and protein including TLR4, CD14, MyD88, NF-kB p65, HIF-1α, VEGF, IL17A, IL6, and inhibiting the accumulation of inflammation." (PMID 36386710, 2022). "Next, eight key targets were identified, including TLR4, CD14, MyD88, NF-κB p65, HIF1 α, VEGF, IL17A, and IL6, which were verified to be key targets for HSSD in the treatment of influenza." (PMID 36386710, 2022). "For instance, Th17 cell effector cytokines (IL-1β, IL-17A, and IL-22) are upregulated in the plasma of patients with laboratory-confirmed A (H3N2) influenza and/or HPIV infections." (PMID 34602860, 2021). "During influenza infection, γδ-T cells acquire reciprocal production of IFN-γ and IL-17A, however, cigarette smoke exposure leads to repression of IFN-γ transcription." (PMID 31354734, 2019).
influenza (continued). "Administration of the novel virus-like particle based vaccine elicited influenza-specific CD4+ and CD8+ T-cell responses and the induction of the cytokines IFN-γ, IL-17A, IL17F, IL-5, IL-13, IL-9, IL-10 and IL-21." (PMID 30573748, 2018). "To assess a protective function of IL-17A against influenza infection in vivo, we found that H1N1 virus-infected Il17a-/- mice exhibited significantly reduced survival rate compared with WT controls." (PMID 26735852, 2016). "Since IL-17A in γδ T cells was shown to be critical for host defence against S. pneumoniae, and influenza virus enhanced sensitivity of mice to secondary S. pneumoniae infection, we proposed that influenza infection may inhibit IL-17A production by γδ T cells in the lung." (PMID 24408967, 2014). "BAL cells and PBMCs from carriage negative volunteers were stimulated with pneumococcal antigens (HK-6B or 6B c/s) or influenza and cytokine (TNF, IL-17A or IFNγ) producing CD4+ memory T-cells were subsequently detected by ICS and flow cytometry." (PMID 23555269, 2013). "Our finding of a strong adaptive-immunity related cytokine response (e.g. CXCL10/IP-10, CXCL9/MIG, IL–17A; and IFN-γ) in seasonal influenza but a relatively suppressed response in severe pH1N1 pneumonia is striking." (PMID 22022504, 2011). "Exposure to aerosols generated from VG/PG with and without nicotine caused greater influenza-induced production in the distal airspaces of the pro-inflammatory cytokines IFN-γ, TNFα, IL-1β, IL-6, IL-17A, and MCP-1 at 7 days post inoculation (dpi)." (PMID 36999019, 2023). "We have previously shown that IL-17A is a critical component of NE-mediated immunity, as IN immunization of IL-17A knock-out mice with NE resulted in severely attenuated nAb responses and no IgA induction in influenza vaccination models (unpublished data)." (PMID 37386041, 2023). "Furthermore, in the lung tissue of mice with influenza, the novel fusion protein vunakizumab-IL22 (vmab-IL-22), a conjugate of IL-22 with anti-IL-17A antibodies, can inhibit IL-17A-mediated inflammatory responses and elevate the reparative capacity of IL-22." (PMID 36839448, 2023). "At 7 dpi with influenza, BAL from mice exposed to e-cigarette aerosol generated from the carrier VG/PG or from VG/PG/Nic had significantly higher levels of IFN-γ, TNFα, IL-1β, IL-6, IL-17A, and MCP-1 compared to mice exposed to air." (PMID 36999019, 2023). "Children with influenza had elevated levels of IL-33, which positively correlated with levels of IL-17A but not with IFN-γ." (PMID 36061377, 2022). "Although other mechanisms may be involved in mediating IL-17A production in γδ T cells, this study has identified γδTCR-IRF4 axis as the crucial mechanism of Tγδ17 induction in the context of influenza infection." (PMID 33772013, 2021). "Similar to the other T cell subsets, IL-17A–producing TCR-γδ+ cells did not significantly increase after stimulation with influenza antigens." (PMID 33497364, 2021). "In addition, hsa-miR-326, hsa-miR-15b-5p, hsa-miR-885, hsa-miR-122-5p, hsa-miR-133a-3p, and hsa-miR-150-5p showed high correlations to IL-6, IL-15, IL-17A, IL-1β, and monocyte chemoattractant protein-1 (MCP-1) with both strains of influenza." (PMID 33540650, 2021). "This direct effect on the classic IL-17A pathway by IAV and its components over and above the late induction of type-I and type-II IFNs may further explain the overwhelming synergy between influenza and extracellular capsular bacteria." (PMID 30192848, 2018). "We found significantly reduced expression levels of IL-17A in lung homogenate in the absence of IL-1β, in both non-infected as well as influenza-infected LPS/elastase exposed mice." (PMID 24918427, 2014). "In summary, influenza infection induced IL-27 production in an IFNAR-dependent pathway, which suppressed innate IL-17A production by γδ T cells upon secondary pneumococcal infection in a STAT1-dependent manner, thereby promoting the development of secondary pneumococcal pneumonia." (PMID 24408967, 2014).
influenza (continued). "We found that influenza-induced neutrophil recruitment to the airways and lung was indeed entirely attenuated 24 h after the infection in absence of IL-17A." (PMID 24918427, 2014). "To confirm that vaccine-primed IL-17A-secreting CD4+ T cells are indeed prototypical Th17 cells, we first assessed the expression of RORγT and T-bet in flu-specific CD4+ T cells in the lungs of mice at 5 days following influenza challenge." (PMID 24465206, 2014). "Examination of CCR6 expression on vaccine-primed Th17 cells demonstrated a heterogenous profile 5 days after influenza challenge with approximately 50% IL-17A+ CD4+ T cells lacking the chemokine receptor." (PMID 24465206, 2014). "Notably, when compared with the seasonal influenza group, the Th1-related CXCL10/IP-10 and CXCL9/MIG, and the Th17-related IL-17A were markedly suppressed in cases of severe pH1N1 pneumonia (2–27 times lower; P−values <0.01)." (PMID 22022504, 2011). "In conclusion, plasma chemokines and cytokine levels prior to or in the first few days post-influenza vaccination may be predictive of serological responses to vaccination, with changes in IFN-γ, IL-17A, and IL-15 post-vaccination possibly indicative of the activation of cell-mediated immunity." (PMID 40881708, 2025). "However, in contrast to our results, in the influenza–tracheal infection model, depletion of the IL-17A–producing Vγ4+CCR6+ γδ T-cell subset did not affect accumulation of NK cells." (PMID 39504049, 2024). "Moreover, the frequency of IL-17A+ and IFNγ+CD8+ T lymphocytes in TBLN-MNC were significantly higher at DPC6 than those of sham-immunized/CA/09-challenged pigs, suggesting induction of influenza-specific CD8+ T cells." (PMID 37112974, 2023). "Of particular importance, the IL-17A-mediated B1-a response is closely correlated with animal survival from H1N1 infection, which may suggest a potential therapeutic target for the treatment of influenza infections." (PMID 26735852, 2016). "In this study, evaluation of TCR expression from antigen-specific IL-17A expressing cells in the lungs or spleens of vaccinated and subsequently influenza infected mice yielded only TCRβ+ cells with little or no IL-17A derived from TCRγδ cells in the lungs and spleens." (PMID 24465206, 2014). "Hence, IL-1β driven neutrophilia during influenza infection of LPS/elastase exposed mice was mediated by IL-17A in the early phase of infection, but became independent of IL-17A." (PMID 24918427, 2014). "IL-17A showed the largest decline differences between MASLD and non-MASLD patients in Legionella (p = 0.0081), influenza (p = 0.0402) and M. pneumoniae (p = 0.0129)." (PMID 40869413, 2025). "In addition, IL-17A- and Th17-associated pathways were highly enriched in 293T cells upon H1N1 IAV infection, indicating that 293T cells are not very prone to triggering host anti-influenza viral responses, although the cell is usually used for packaging virus." (PMID 31681209, 2019). "PBMCs from pneumococcal colonised (n = 10) and non-colonised (n = 8) adults stimulated ex vivo with influenza antigen elicited similar frequencies of TNF+, IL-17A+ and IFNγ+ CD4+ memory T-cells." (PMID 23555269, 2013).